MTOR (mechanistic target of rapamycin kinase)
Diseases named in the same sentence as MTOR in open-access papers (continued):
Sharing a sentence is not in itself a finding about the gene and the disease.
tumor (continued). "IL-8 and mTOR counter oxidative stress by inhibiting GSK-3β, while IL-17 stimulates matrix metalloproteinase 7 (MMP7) expression, driving tumor progression through epithelial-mesenchymal transition." (PMID 40430079, 2025). "The application of PI3K inhibitors in GBM is actively researched, as the PI3K/AKT/mTOR pathway is often hyperactivated in GBM and critical for tumor growth, survival, migration, and invasion." (PMID 40076844, 2025). "Mechanistically, the edited COPA (COPA^I164V) attenuates tumor growth by suppressing the PI3K/AKT/mTOR pathway via downregulation of Caveolin-1 (CAV1), thereby decreasing mTOR-driven cell proliferation and survival." (PMID 40852728, 2025). "We also summarize the drug therapeutic trials and related nanomaterials that can be retrieved to target aging and tumor‐related signaling pathways, with the research focusing on the PI3K/mTOR, AMPK, and Notch signaling pathway." (PMID 40046406, 2025). "HOTAIR promotes invasion, tumor growth, and metastasis through multiple pathways, including the PI3K/Akt/mTOR signaling pathway, which is crucial for cellular metabolism." (PMID 39858015, 2025). "Sirolimus, the first mTOR inhibitor, not only inhibits AML growth but can also significantly reduce tumor volume in some cases." (PMID 40823555, 2025). "We concluded that CALCA acts as a tumor suppressor in pNETs, inhibiting cell proliferation and angiogenesis by downregulating the PI3K/AKT/mTOR signaling pathway." (PMID 41281753, 2025). "In a mouse model of AS, combined inhibition of mTOR (rapamycin) and MEK (trametinib) led to sustained tumor regression compared to monotherapy with either agent alone." (PMID 40666093, 2025). "Studies have reported that the mTOR signaling pathway is involved in the pathophysiology of MM, and a small mTOR inhibitory molecule (SC06) was found to induce the inhibition of tumor growth in an in vivo model of MM." (PMID 38254747, 2024). "Similar effects on tumor angiogenesis have been observed with luteolin, as it reduces phosphorylated VEGFR2 induced by VEGF-A and inhibits subsequent proteins including mTOR, AKT, P70S6K, ERK, MMP-2, and MMP-9." (PMID 38611849, 2024). "As for the other MKIs and selective kinase inhibitors, especially selective kinase inhibitors that restore RAI uptake in tumor cells (such as BRAF, MEK and mTOR inhibitors), encouraging results are shown in multiple clinical trials." (PMID 39473507, 2024). "Meanwhile, a synergistic antiproliferative effect has been reported for the combined use of an mTOR inhibitor and MEK inhibitor in tumor cells." (PMID 38253821, 2024). "These signaling cascades, including MAPK, JAK-STAT, and EGFR/PI3K/Akt/mTOR, orchestrate key oncogenic processes, while dysregulation in pathways like Wnt/β-catenin, VEGF/VEGFR, and NF-κB promotes tumor progression and angiogenesis." (PMID 39682234, 2024). "mTOR activation in HCC strongly correlates with poor tumor differentiation, poor prognosis and early tumor recurrence." (PMID 38177295, 2024). "Mechanistically, W. coagulans MZY531 postbiotics inhibit tumor growth through the modulation of the Bax/Bcl-2/caspase-3 and JAK2/STAT3 apoptosis pathways and PI3K/AKT/mTOR and TGF-β/SMAD4 cell autophagy pathways." (PMID 39459634, 2024). "We observed that kinase activity profiles varied between tumor intrinsic subtypes, with a highly hyperactive Phos2 (hyperactivity of PI3K/AKT and mTOR signaling members, PTK2, SRC, EPHA2 kinases) and a less active Phos1 subtype." (PMID 38650175, 2024). "Control of HIF-1α expression by mTOR has been previously established, astreatment with Rapa can inhibit HIF-1α in tumor cells." (PMID 38767353, 2024).
tumor (continued). "Firstly, TAMs can regulate the expression of certain autophagy-related signaling molecules such as mTOR, AKT, and MAPK, thereby controlling the level of autophagy in tumor cells." (PMID 38675475, 2024). "A combination between BET and mechanistic target of rapamycin kinase (mTOR) inhibition has also been proposed, as BET inhibitors can inadvertently promote tumor survival by upregulating the mTOR pathway." (PMID 39456533, 2024). "Bupivacaine inhibited tumor cell proliferation and migration through AKT/mTOR signaling pathway to increase the expression of Beclin-1 and the expression ratio of light chain 3B-II (LC3B-II)/LC3B-I in NSCLC cells." (PMID 38482052, 2024). "mTOR also regulates angiogenesis through vascular endothelial growth factor (VEGF) production, ensuring an adequate blood supply for the expanding tumor mass in HCC." (PMID 39840041, 2024). "IHC stainings showed increased mTORC1 activity: significantly increased p-mTOR, p-S6 and a slight increase in Rictor and p-Ser473-Akt were observed in TAC treated tumours." (PMID 38341510, 2024). "Our finding for the tumor would need to be verified by testing PI3K/AKT and MTOR activities in skeletal muscle tissue." (PMID 39769193, 2024). "In conclusion, berberine's chemopreventive and tumor‐suppressive properties on CRC occur through multiple mechanisms on the several pathways, such as mTOR, and Wnt‐ β‐catenin." (PMID 39723045, 2024). "In patients with tumor, the PI3K/Akt/mTOR signaling pathway often exhibits overactivation, primarily due to dysregulation in the expression of PIK3CA and phosphatase and tensin homolog (PTEN)." (PMID 39119480, 2024). "There are many mechanisms that regulate PD-L1 expression in the tumor microenvironment, and the PI3K-Akt-mTOR pathway is involved in PD-L1 expression." (PMID 38370876, 2024). "Through CREB1-mediated PI3K/Akt/mTOR signaling, UCA1 upregulates the expression of CREB1, competitively binds miR-582, and accelerates EMT pathway, thereby boosting tumor metastasis." (PMID 39119480, 2024). "In such instances, a 3‐month treatment course with an mTOR inhibitor has been shown to improve the outcome of LT for HCC, especially in patients with evidence of high AFP activity within the tumor." (PMID 38250695, 2024). "This enrichment for PI3K/AKT/mTOR signaling in our study was validated with immunohistochemistry for phosphorylated AKT and in vitro cell culture assays evaluating tumor cell survival and proliferation following treatment with a PI3K inhibitor." (PMID 38166662, 2024). "An inverse relationship between the expression of miR-99b-5p and mTOR has been described either in BCCL and tumor specimens." (PMID 38338777, 2024). "Treatment of SEGAs involves a combination of surgical resection and targeted medical therapy with MTOR inhibitors such as everolimus that inhibits the mTOR pathway which is overactive in TSC and contributes to tumour growth." (PMID 38206395, 2024). "Pearson correlation was calculated for the expression levels of the gene pairs – FER and mTOR and FER and LARP1 in both tumor and healthy tissues." (PMID 39206154, 2024). "As an upstream regulatory factor, immature IGF-1R loses its ability to activate the PI3K/Akt/mTOR and MAPK/ERK pathways, thereby limiting tumor cell proliferation." (PMID 39199143, 2024). "Moreover, given MTOR’s pivotal role in nutrient sensing and metabolic reprogramming, its inhibition may simultaneously reduce tumor resilience to therapeutic interventions and sensitize tumors to existing treatment modalities, ultimately improving patient outcomes." (PMID 39742278, 2024).
tumor (continued). "Preclinical research in GBM has revealed that combining an EGFR inhibitor with a mTOR inhibitor can modulate the TME by downregulating immunosuppressive chemokines and inhibiting tumour-promoting macrophage infiltration." (PMID 39272879, 2024). "The high mutation burden observed in genes strongly suggests a potential interplay between PI3K-Akt-mTOR signaling and ECM, contributing to tumor cell function and the establishment of a tumor-supportive microenvironment in IECs." (PMID 39456581, 2024). "Studies have validated that the concurrent use of ATP-competitive inhibitors to target the AKT/mTOR pathway and HER2 inhibitors can induce apoptosis in tumor cells and result in tumor shrinkage, with these effects being sustained over time." (PMID 39769140, 2024). "The enriched signaling pathways involved in cell cycles, namely, PIP3-activated AKT signaling, mTOR signaling, WNT signaling, and MAPK activation, suggested that the manipulation of tumor growth was significantly changed in the NOD.SCID mice." (PMID 38672200, 2024). "Immunohistochemistry revealed that the LC3 and LAMP1 expression increased, but the mTOR and MET expression decreased in IL-32γ-overexpressing mouse tumor tissues." (PMID 39519229, 2024). "The PI3K/AKT/mTOR signaling pathway is frequently activated in NSCLC and plays a crucial role in tumor development by promoting cell survival, growth, proliferation, and migration." (PMID 39518013, 2024). "EBV, and more precisely, its oncoproteins, initiate tumor formation by modulating many signaling pathways, such as NF-κB, JAK/STAT, Wnt/β-catenin, PI3k/Akt/mTOR and EGFR/MAPK." (PMID 39001390, 2024). "The activation of the phosphatidylinositol 3-kinase/protein kinase B/mechanistic target of rapamycin (PI3K/AKT/mTOR) pathway eventually leads to activation of mTORC1/2, leading to cell survival, proliferation, and neoplasia." (PMID 38676718, 2024). "Specifically, FH deletion suppresses AMPK activation to further cross‐activate mTOR and ACC thus promoting lipid biosynthesis to provide energy material for tumor growth." (PMID 39584783, 2024). "Meanwhile, three targeted genes (AKT1, MTOR and PIK3CG) of these drugs showed significant upregulation in SLC12A5‐low tumour." (PMID 38685685, 2024). "The mTOR pathway, downstream of PI3K/AKT, directs serine-threonine protein kinase, thereby modulating tumor cell proliferation, invasion, and metastasis via ribosomal protein kinase activation." (PMID 38291517, 2024). "Combining mTOR and c-MET inhibitors has demonstrated synergistic effects in reducing tumor growth in preclinical models, offering a new therapeutic strategy for this condition." (PMID 39329778, 2024). "Additionally, CD109’s interaction with EGFR could amplify pro-inflammatory cytokine production, such as IL-6 and IL-8, by activating downstream pathways like Akt/mTOR and NF-κB, thereby enhancing tumor growth, immune suppression, and potentially contributing to chemoresistance." (PMID 39990858, 2024). "By regulating these factors, the PI3K/Akt/mTOR pathway can promote or inhibit the EMT process of cells, thereby affecting tumor metastasis and invasion." (PMID 38916406, 2024). "Everolimus inhibits PI3K/AKT/mTOR and hypoxia-inducible factor 1-alpha (HIF 1α), an important factor that promotes angiogenesis and tumor growth." (PMID 38339127, 2024). "JAK-STAT1, PI3K/Akt/mTOR and Ras/Raf/MEK/ERK, which are three cardinal signaling pathways, play similar crucial biological roles in cell survival, proliferation and tumor formation, growth and metastasis." (PMID 39664585, 2024). "In silico analysis of human MB tumor samples reinforced the clinical relevance, revealing a robust positive correlation between OTX2 and mTOR mRNA expressions across diverse datasets." (PMID 38674001, 2024). "This activation inhibits the mTOR inhibitor DEPTOR, contributing to tumor growth and drug resistance." (PMID 38292868, 2024).
tumor (continued). "Our findings revealed that ANP32E aggravated CRC tumor growth and glycolysis through stimulating the AKT/mTOR pathway." (PMID 38585643, 2024). "For example, in triple-negative breast cancer, EGFR influences the EMT marker MMP2 by activating the PI3K/AKT/mTOR pathway, while MMP9 expression facilitates tumor metastasis." (PMID 39593172, 2024). "The mechanism by which PA inhibits tumor growth in vivo involves increasing cellular stress and apoptosis, reducing angiogenesis, and inhibiting AKT/mTOR and MAPK pathway activity." (PMID 38786008, 2024). "In summary, we conclude that in both the IDH1 MT human primary tumor cell lines and in the murine model VPA inhibits growth at least partially via inhibition of the mTOR pathway and that the mTOR pathway is involved in downregulation of FASN." (PMID 39149696, 2024). "In a word, this report suggests that lidocaine promotes autophagy in neural cells to inhibit tumor development by regulating the expression of miR-145 and further inactivating the PI3K/AKT/mTOR signaling pathway." (PMID 38482052, 2024). "Notably, we identified a relatively higher enrichment of the mTOR pathway in tumor-infiltrating myeloid cells (monocytes/macrophage) compared to the other immune cell clusters, supporting the notion that mTOR signaling may play a role in modulating the activity of these cells within the TME." (PMID 39766137, 2024). "Multiple mechanisms, including NF‐κB signalling, p38MAPK signalling, mTOR signalling, ATM signalling and autophagic activity, have been reported to mediate these regulatory effects in senescent tumour cells." (PMID 39270064, 2024). "The western blotting results of tumor tissue proteins suggested that ICA also increased the phosphorylation of AMPK and ULK1 while reducing the expression of phosphorylated mTOR protein in vivo." (PMID 38355608, 2024). "Inhibition of the mTOR pathway, such as rapamycin (RAPA), has been investigated to reinduce anti-tumor immune activity." (PMID 38720342, 2024). "mTOR is a serine/threonine kinase belonging to the phosphoinositide 3-kinase-related kinase (PIKK) family, playing a pivotal role in tumor growth, metastasis, and drug resistance." (PMID 39749199, 2024). "AMPK activation was found to lead to the inhibition of the mammalian target of rapamycin (mTOR), a downstream target of AMPK, which can promote tumour growth." (PMID 39199548, 2024). "These anti-tumor effects are achieved through strategic modulation of pivotal signaling cascades, particularly the PI3K/Akt/mTOR, MAPK, and NFκB pathways." (PMID 39274982, 2024). "Combination treatment with a dual pan-PI3K/mTOR inhibitor and a MEK1/2 inhibitor showed the stabilization of tumor growth in one model." (PMID 39682182, 2024). "Previous studies have also found that anlotinib can promote tumor cell apoptosis through Erk, BTK, PI3K/AKT/mTOR signaling pathways." (PMID 39193386, 2024). "The PI3K/AKT/mTOR signaling pathway has cross-talk with the Ras/Raf/MAPK (MEK)/ERK pathway and tumor suppressor gene pathway: PI3K, a family of lipid kinases and class IA PI3Ks, which comprises a catalytic p110 subunit and a regulatory p85 subunit." (PMID 38785748, 2024). "It has been reported that anti-PD-1 combined with endostar has a synergistic effect, dramatically suppressing tumor growth by upregulating cell apoptosis and PI3K/AKT/mTOR-mediated autophagy." (PMID 38257275, 2024). "In general, cancer signaling is highly complex, forming interconnected circuits that drive oncogenesis, tumor progression, and metastasis, often involving cross-talk between cascades like PI3K/AKT/mTOR, WNT/RAS/RAF/MEK/ERK, and TNFα/SMAD." (PMID 39682281, 2024).
tumor (continued). "In tumor cells, AMPK activation can repress the PI3K/AKT/mTOR pathway, thereby inhibiting cell growth and tumorigenesis." (PMID 39195514, 2024). "OPN expression through Akt/mTOR and MNK/eIF4E pathways triggers infiltration of suppressive MDSCs, thereby creating an immune-suppressive TME and promoting tumor proliferation in prostate cancer." (PMID 39062100, 2024). "Lactate dehydrogenase (LDH), a metabolic enzyme involved in glycolysis, is regulated by the PI3K/Akt/mTOR pathways, the MYC oncogenic transcription factor, tumor hypoxia, and necrosis." (PMID 39435278, 2024). "The PI3K/AKT/mTOR and RAF/MEK/ERK pathways commonly undergo activation and dysregulation across nearly all types of neoplasms, often exhibiting alterations in their various components." (PMID 39203892, 2024). "The drug has been proposed to have anti-cancer activities by acting directly on tumor cell metabolism, in particular through the inhibition of oxidative phosphorylation of tumor cell mitochondria, and by acting as a PI3K-Akt-mTOR pathway inhibitor." (PMID 38279016, 2024). "With the administration of chemotherapy or other anti-tumor treatment, PI3K/Akt/mTOR signaling is suppressed, forcing GBM cells to activate autophagy as a protective response." (PMID 38890642, 2024). "Upregulation of EGFR leads to activation of EGFR signaling and promotes tumor progression through EGFR downstream pathways, including PI3K/Akt/mTOR and RAS/MEK/ERK pathways." (PMID 39036344, 2024). "Through PI3K/AKT/mTOR signaling, STEAP2 downregulation can promote tumor cell proliferation and metastasis." (PMID 38478326, 2024). "Chen et al35 reported that in LAUD, CCAT1/FABP5 promotes tumour progression by mediating fatty acid metabolism and stabilizing PI3K/AKT/mTOR signalling." (PMID 38506080, 2024). "Treatment with RXRs agonists, such as bexarotene, inhibits tumor angiogenesis, suppresses the proliferation and migration of lung tumor cells, and promotes tumor cell death through the PPARγ, PTEN, and mTOR pathways." (PMID 39311119, 2024). "Through the GPR81/mTOR/HIF-1a/STAT3 pathway, lactate stimulates the activity of MDSCs, leading to increased expression of genes that promote tumor growth and immunosuppressive effects on T cells." (PMID 38933335, 2024). "This is most likely due to the fact that the majority of PI3K/mTOR inhibitors are unable to pass the BBB and achieve adequate concentrations at the tumour site." (PMID 39272879, 2024). "Our analysis of in vivo tumor tissues by RT-qPCR showed Setd7 KO and CPH-treated mice showed attenuated apoptotic and metastatic pathways such as Akt/mTOR and MMPs." (PMID 39522095, 2024). "The tumor control group showed a remarkable upregulation for PI3K, p-AKT, and p-mTOR, along with downregulation for the antioxidant SOD and GPX4, as well as decreased levels of GSH and MDA." (PMID 39519654, 2024). "Cul7 also exerts a tumor suppressor effect, as evidenced in part by the degradation of IRS-1 via the mTOR pathway." (PMID 39852134, 2024). "This is explained by the fact that secondary signal transducers correlated to tumor suppressors (such as SIRT1) or potential oncogens (for example, mTOR, and KRAS) behave pleiotropically depending on the tissue or cell type." (PMID 39203892, 2024). "Tumors formed by GH4C1 cell lines carrying different genotypes exhibited varying levels of mTOR pathway activation and growth rates.EVE reduced tumor volume, lowered GH levels, and inhibited p-S6." (PMID 39736867, 2024). "In contrast, PI3K/mTOR inhibition induced profound tumour microenvironment remodelling in an ICB‐resistant humanized uLMS PDX model, fostering adaptive anti‐tumour immune responses." (PMID 38711203, 2024). "Metformin’s mechanism of action through the AMPK pathway and its effects on the mTOR/S6K1 axis suggest comprehensive anti-tumoral activity, from reducing cell viability to modifying the tumor’s edema and microenvironment." (PMID 38891882, 2024).